OSTN-AS1 (OSTN antisense RNA 1)
Gene: Long non-coding RNA gene on chromosome 3 (191,213,290 to 191,261,138, reverse strand). Ensembl gene ENSG00000233308.
Diseases named in the same sentence as OSTN-AS1 in open-access papers:
OSTN-AS1 is named in the same sentence as 1 disease in open-access papers, as found by Europe PMC text mining. Sharing a sentence is not in itself a finding about the gene and the disease.
OSTN-AS1 shares sentences with these, for which no sentence is quoted: cancer (1 paper).